USB1 (U6 snRNA biogenesis phosphodiesterase 1)
Description:
3'-5' RNA exonuclease that trims the 3' end of oligo(U) and oligo(A) tracts of the pre-U6 small nuclear RNA (snRNA) molecule, leading to the formation of a mature U6 snRNA 3' end-terminated with a 2',3'-cyclic phosphate. Participates in the U6 snRNA 3' end processing that prevents U6 snRNA degradation. In addition also removes uridines from the 3' end of U6atac snRNA and possibly the vault RNA VTRNA1-1.
Synonyms: hUsb1; hMpn1; C16orf57; Mpn1; FLJ13154; HVSL1; PN
Tractability: Small molecule: a structure with a bound ligand is known.
Gene: Protein-coding gene on chromosome 16 (57,999,546 to 58,021,618, forward strand). Ensembl gene ENSG00000103005.
Subcellular location: Nucleus
Subcellular location (Human Protein Atlas): Nucleoplasm
Gene Ontology:
Molecular function: 3'-5'-RNA exonuclease activity; poly(U)-specific exoribonuclease activity, producing 3' uridine cyclic phosphate ends; protein binding; nuclease activity
Biological process: RNA splicing; snRNA 3'-end processing; U6 snRNA 3'-end processing
Cellular component: nucleoplasm; nucleus
Genetic constraint (gnomAD): Loss-of-function variants: 19 observed, 27.44 expected, observed/expected ratio (o/e) 0.69, 90% interval 0.48 to 1.02. The upper end of that interval is the gene's LOEUF score, 1.02, which puts it in group 4 of 6, group 1 being the genes least tolerant of losing a copy. Missense variants: 318 observed, 347.73 expected, observed/expected ratio (o/e) 0.91, 90% interval 0.83 to 1. Synonymous variants: 141 observed, 136.14 expected, observed/expected ratio (o/e) 1.04, 90% interval 0.9 to 1.19.
Homologues: Orthologues: macaque USB1 (96% identical), chimpanzee USB1 (92% identical), pig USB1 (84% identical), rat Usb1 (83% identical), guinea pig USB1 (83% identical), mouse Usb1 (81% identical), dog USB1 (77% identical), tropical clawed frog usb1 (50% identical), zebrafish usb1 (47% identical), Drosophila melanogaster CG16790 (35% identical).
Diseases named in the same sentence as USB1 in open-access papers:
USB1 is named in the same sentence as 25 diseases in open-access papers, as found by Europe PMC text mining. Sharing a sentence is not in itself a finding about the gene and the disease. The quoted sentences say what the papers report.
neutropenia (12 papers, 2012 to 2026). A decrease in the number of neutrophils found in the blood. "Mutations in the C16orf57 gene, which encodes the USB1 protein, are implicated as the underlying cause of poikiloderma with neutropenia." (PMID 39810212, 2025). "For example, loss-of-function mutations in USB1 (USB1 mutants) lead to the genetic disorder Poikiloderma with Neutropenia (PN), an autosomal-recessive bone marrow failure (BMF) syndrome with marked clinical overlap with Dyskeratosis Congenita (DC)." (PMID 37544646, 2023). "Mutations in the 3’ to 5’ RNA exonuclease USB1 cause hematopoietic failure in Poikiloderma with Neutropenia (PN)." (PMID 36862787, 2023). "U6 snRNA biogenesis phosphodiesterase 1 (USB1), also known as C16orf57, is mutated in poikiloderma with neutropenia (PN) and dyskeratosis congenita (DC)." (PMID 33816259, 2021). "Loss of function mutations in human Usb1 cause the rare disorder poikiloderma with neutropenia (PN), and result in U6 snRNAs with elongated 3′ ends that are aberrantly adenylated." (PMID 30215753, 2018). "Loss of function mutations in the human USB1 gene result in the rare genetic disorder poikiloderma with neutropenia (PN)." (PMID 30215753, 2018). "In contrast, neutropenia, marked by low neutrophil counts, is often associated with mutations in ELANE and USB1." (PMID 41141324, 2025). "As PN is usually associated with severe non-cyclic neutropenia, we analyzed the potential of neutrophil formation in WT and USB1 mutant cells." (PMID 36862787, 2023). "Two genes, Usb1 and Lrig3, have recently been studied as therapeutic targets in poikiloderma with neutropenia and prostate cancer, respectively, while Ica1 encodes an autoantigen involved in autoimmune insulin-dependent diabetes mellitus and primary Sjogren’s syndrome." (PMID 36818345, 2023). "Because PN is a possible differential diagnosis in the presence of poikiloderma, we sequenced the USB1 gene in all patients with only one or no RECQL4 mutation and in one patient with poikiloderma and neutropenia." (PMID 27247962, 2016). "Due to growth retardation, poikiloderma-like skin lesions on face, neck and limbs, nail dystrophy, hypotrichosis and recurrent infections the USB1 (OMIM*613276) gene, responsible for Poikiloderma with Neutropenia (PN; OMIM#604173) was tested, but no mutations were detected." (PMID 27717396, 2016).
dyskeratosis congenita (5 papers, 2012 to 2025). Dyskeratosis congenita (DC) is a rare ectodermal dysplasia that often presents with the classic triad of nail dysplasia, skin pigmentary changes, and oral leukoplakia associated with a high risk of bone marrow failure (BMF) and cancer. "In addition to its involvement in cancer, mutations in the 3′-end processing enzymes, PARN and USB1, were implicated in the human diseases, dyskeratosis congenita (DC) and poikiloderma with neutropenia (PN), respectively." (PMID 40243428, 2025). "Mehr als 14 Genmutationen wurden mit einer Dyskeratosis congenita in Verbindung gebracht (DKC1, TERC, TERT, NOP10, NHP2, TINF2, C16orf57/USB1, TCAB1, CTC1 und RTEL1)." (PMID 37650893, 2023).
pontocerebellar hypoplasia type 7 (2 papers, 2023 to 2024). "Functions of these enzymes are central to human health, with TOE1 mutations associated with Pontocerebellar Hypoplasia Type 7 (PCH7), PARN mutations with Dyskeratosis Congenita and other human disorders, PNLDC1 mutations with azoospermia, and USB1 mutations with Poikiloderma with neutropenia." (PMID 38194449, 2024).
acute myeloid leukaemia (1 paper, 2015). "Targeted analysis of usb1-deficient zebrafish might lend insights suitable to be translated into therapies for the human disorder, particularly concerning the predisposition to myelodysplasia and acute myeloid leukaemia." (PMID 26522474, 2015).
Hepatic fibrosis (1 paper, 2024). The presence of excessive fibrous connective tissue in the liver. "Among these, the mRNA levels of nine genes, including USB1, NT5E, RORA, SDK1, and IL10, were significantly up-regulated, suggesting their involvement in the miRNA-30-mediated regulation of host hepatic fibrosis." (PMID 39139565, 2024).
Immunodeficiency (1 paper, 2026). Failure of the immune system to protect the body adequately from infection, due to the absence or insufficiency of some component process or substance. "Strikingly, exome sequencing also revealed variants in immunodeficiency-associated genes (IRAK4, USB1), autoinflammatory disorders (PSTPIP1) and unexpected candidates like ETV6, and MAN1B1 revealing previously unrecognised pathways in SLE development." (PMID 41930824, 2026).
Kindler syndrome (1 paper, 2022). Kindler syndrome (KS) is the fourth major type of epidermolysis bullosa (EB), besides simplex, junctional and dystrophic forms, and is characterized by skin fragility and blistering at birth followed by development of photosensitivity and progressive poikilodermatous skin changes. "In addition, Kindler syndrome (OMIM #173650) due to FERMT1 gene mutations, and poikiloderma with neutropenia type Clericuzio (OMIM #604173), associated with biallelic mutations in USB1 gene." (PMID 35328050, 2022).
thyroid cancer (1 paper, 2021). "We found six RBPs (AZGP1, IGF2BP2, MEX3A, NUDT16, NUP153, USB1) independently associated with prognosis of patients with thyroid cancer according to univariate and multivariate Cox proportional hazards regression models." (PMID 33816259, 2021).
thyroid tumor (1 paper, 2021). A benign or malignant neoplasm affecting the thyroid gland. "Moreover, experimental validation confirmed that NUP153 and USB1 impact the growth of thyroid tumor cell lines." (PMID 33816259, 2021).
cancer (1 paper, 2021). A tumor composed of atypical neoplastic, often pleomorphic cells that invade other tissues. "Finally, biological experiments disclosed that NUP153 and USB1 can significantly impact cancer cell proliferation and migration." (PMID 33816259, 2021).
USB1 also shares sentences with these, for which no sentence is quoted: poikiloderma with neutropenia (6 papers); osteopetrosis (3); Nail dystrophy (2); Rothmund-Thomson syndrome (2); genetic disorder (1); glioma (1); hypotrichosis (1); leukaemia (1); Mycoplasma Infections (1); Myelodysplasia (1); myelodysplastic syndrome (1); Myeloma (1); primary Sjogren’s syndrome (1); prostate carcinoma (1); Tumor (1).